TLR2 (toll like receptor 2)
Diseases named in the same sentence as TLR2 in open-access papers (continued):
Sharing a sentence is not in itself a finding about the gene and the disease.
vulvovaginal candidiasis (5 papers, 2014 to 2026). Infection of the vulva and vagina with a fungus of the genus CANDIDA. "The Pro631His (rs5743704) SNP in TLR2 has been implicated in the development of idiopathic recurrent vulvovaginal candidiasis (RVVC)." (PMID 41295183, 2025). "Within the same context, another study suggested that gene polymorphism in Toll like receptor 2 reduces the production of IL-17 and thereby increases susceptibility to recurrent vulvovaginal candidiasis." (PMID 36449073, 2023). "albicans, impacting fungal adaptations, including morphogenesis and biofilm formation, virulence, and host immune responses, such as the epithelial TLR2/4-MyD88-NF-κB activation in the murine model of vulvovaginal candidiasis." (PMID 41837434, 2026). "albicans and host inflammatory responses; the latter was possibly via the TLR2/4-MyD88-NF-κB pathway.IMPORTANCEEffective management of vulvovaginal candidiasis requires a comprehensive understanding of virulence genes in C." (PMID 41837434, 2026). "STRING analysis demonstrated that SYK, TLR4, CARD9, and TLR2 are involved in vulvovaginal candidiasis and infectious disease pathways." (PMID 37238269, 2023). "Genetic association of recurrent vulvovaginal candidiasis (RVVC) with polymorphisms in DECTIN-1, CARD9, TLR1, TLR2, and TLR4 genes." (PMID 25295030, 2014).
airway hyperresponsiveness (4 papers, 2011 to 2022). "TLR2 plays a key role in the development of airway hyperresponsiveness and of chronic airway inflammation after infection." (PMID 35372108, 2022). "TLR2 is reported to play a pro-allergic role in the allergic host, and stimulation of TLR2 ligand augments Th2 responses and exacerbates airway hyperresponsiveness (AHR)." (PMID 21364926, 2011). "However, TLR2 stimulation by its ligands was reported to potentiate Th2 responses and exacerbate airway hyperresponsiveness." (PMID 27084682, 2016).
allergic rhinitis (4 papers, 2015 to 2025). Inflammation of the nasal mucous membranes caused by an IgE-mediated response to external allergens. "β-glucans in HDM activate TLR2 in nasal epithelial cells to promote allergic rhinitis via DUOX2/ROS-mediated signaling." (PMID 40529570, 2025). "Up-regulation of IL-12 production by macrophages stimulated with OK-432 via TLR2 in vivo seemed to successfully inhibit the Th2 augmentation at induction phase of murine allergic rhinitis model." (PMID 30486312, 2018). "From our data, OK-432 induces IL-12 production from macrophages via TLR2 and inhibits Th2 responses and atopic inflammation, including allergic rhinitis." (PMID 30486312, 2018). "We also examined the effect of OK-432 on Th2 responses and allergic rhinitis in TLR2 knock-out mice in comparison with wild-type of C57BL/6 mice." (PMID 30486312, 2018). "In our present study, the role of TLR2 for the recognition of OK-432 by macrophages and the effects of OK-432 are examined on murine allergic rhinitis model." (PMID 30486312, 2018). "Moreover, in TLR2 ko mice, no regulatory effect of OK-432 was observed on an allergic rhinitis model." (PMID 30486312, 2018).
bacterial pneumonia (4 papers, 2012 to 2023). Acute infection of the lung parenchyma caused by bacteria (e.g., Streptococcus pneumoniae, Haemophilus influenzae, Chlamydia pneumoniae, Mycoplasma pneumoniae, and Legionella pneumophila). "We have reported that only class C CpG ODNs can effectively activate TLR9 in a manner that synergizes with TLR2/6 to protect against bacterial pneumonia." (PMID 22299046, 2012). "In conclusion, CME can play a therapeutic role in LTA-induced inflammation in MH-S cells via TLR2/NF-κB/NLRP3, and may serve as a potential drug for bacterial pneumonia caused by Gram-positive bacteria." (PMID 37958501, 2023).
Coccidioides infection (4 papers, 2015 to 2023). "TLR2−/− mice are more susceptible to primary Coccidioides infection compared to their wild-type counterparts, indicating that TLR2 contributes to the initial recognition of spherules." (PMID 28300772, 2017). "Data from six dogs with coccidioidomycosis (pulmonary, n = 4; disseminated, n = 2) were excluded from the analysis of TLR2 and TLR4 expression because of technical difficulties." (PMID 36836327, 2023). "Ampel demonstrated that PBMCs from humans with coccidioidomycosis produced lower concentrations of TNF-α when TLR2 and TLR4 were blocked with antibody during stimulation with the coccidioidal extract, T27K, a complex glycoprotein antigen mixture." (PMID 36836327, 2023). "Both TLR2−/− and wild-type WT mice are similarly protected by a live-attenuated (ΔT) vaccine, suggesting that unidentified complementary PRRs are involved in guiding the development of adaptive immunity against coccidioidomycosis." (PMID 28300772, 2017). "antigen-stimulated leukocyte cytokine production to assess the inflammatory profile, TLR2 and TLR4 expression, and serum CRP concentrations between dogs with newly diagnosed coccidioidomycosis and seronegative healthy controls." (PMID 36836327, 2023). "We hypothesized that cytokine concentrations, serum CRP concentration, and leukocyte TLR2 and TLR4 expression would be different between dogs with coccidioidomycosis and healthy controls." (PMID 36836327, 2023). "While a T-cell intrinsic role was not explored, IL-1R but not TLR2 signaling was essential for Th17 responses during Coccidioides infection." (PMID 26367276, 2015). "Moreover, it was also demonstrated that the IL-1 receptor, but not TLR2, is essential to developing a Th17 immunity response against Coccidioides infection, a mechanism mediated by MyD88." (PMID 33425780, 2020).
coronary atherosclerosis (4 papers, 2019 to 2022). Atherosclerosis of the coronary vasculature. "Here, we report a robust correlation of cardiac PAR1 and TLR2/4 expression in patients with coronary atherosclerosis." (PMID 34944024, 2021). "In our current study, we found that TLR2 is related not only to the severity of coronary atherosclerosis but also to the vulnerability of plaques." (PMID 33574831, 2020). "Our results suggest elevated TLR2 mRNA expression in platelets as a biomarker reflecting the underlying inflammation in ACS and possibly severity of coronary atherosclerosis." (PMID 31644579, 2019). "TLR2 may have a crucial role in the progression from coronary atherosclerosis to MI." (PMID 35840880, 2022). "TLR2 may have a crucial role in progressing from coronary atherosclerosis to MI." (PMID 35840880, 2022). "Myocardial PAR1 expression strongly correlated with TLR2 and TLR4 in patients with coronary atherosclerosis." (PMID 34944024, 2021). "In the current study, we used integrated WGCNA methods to analyze the dataset and identify two hub genes (TLR2 and CD14) that were positively correlated with the severity of coronary atherosclerosis." (PMID 33574831, 2020). "We found that mRNA expression levels of TLR2 but not TLR 4 and 9 are up-regulated in platelets of patients with ACS when compared to patients without coronary atherosclerosis." (PMID 31644579, 2019).
cysticercosis (4 papers, 2016 to 2023). "A cysticercosis experiment in a previous study demonstrated that the lack of Th1-dominant adaptive immunity in TLR2−/− mice were associated with significantly elevated parasite burdens." (PMID 37600806, 2023). "Of them, the heterodimer of TLR2/TLR6 might participate in recognition of the T. regenti infection similarly to murine neurocysticercosis." (PMID 35120185, 2022). "Additionally, among all TLRs, TLR2 expression was induced first and was substantially upregulated in the brain during murine neurocysticercosis." (PMID 27511368, 2016).
disc degeneration (4 papers, 2021 to 2025). "The reduction in senescence, SASP, and TLR-2 expression suggest o-vanillin as a potential disease-modifying drug for patients with disc degeneration and back pain." (PMID 33863359, 2021). "This suggests a potential role of TLR2 signaling in CEPs in disc degeneration and MC1." (PMID 39272974, 2024). "In accordance with the reported association between increased TLR expression and increased degree of disc degeneration and pain, double staining for p16INK4a and TLR-2 revealed their co-localization in human TLR-2/6 activation-induced senescent IVD cells from non-degenerate and degenerated tissues." (PMID 38535306, 2024). "Enhanced TLR2 expression in MC1, and generally in CEPCs under inflammatory conditions, has pro-inflammatory and pro-catabolic effects, suggesting a potential role in disc degeneration and MC." (PMID 39272974, 2024). "Taken together our data demonstrate that activation of TLR-2/6 induce senescence and increase TLR-2 and SASP expression in cells from non-degenerate IVDs of organ donors without degeneration and back pain and in cells from degenerating human IVD of patients with disc degeneration and back pain." (PMID 33863359, 2021). "We showed that TLR-2/6 activation increased TLR-2 expression and senescent cells in IVD cells from both organ donors without degeneration and back pain and patients with disc degeneration and back pain." (PMID 33863359, 2021).
esophageal cancer (4 papers, 2015 to 2025). A primary or metastatic malignant neoplasm involving the esophagus. "For example, in esophageal cancer, increased expression of TLR3, TLR4, TLR7, and TLR9 has been linked to esophageal squamous cell carcinomas, while TLR1, TLR2, TLR4, and TLR6 are often overexpressed in esophageal adenocarcinoma." (PMID 40109582, 2025). "For example, Porphyromonas promotes cell proliferation or inflammatory responses via interaction with TLR2 or TLR4 in preclinical models, and is associated with the prognosis of lung or esophageal cancer." (PMID 38304032, 2023).
food allergy (4 papers, 2014 to 2024). Gastrointestinal disturbances, skin eruptions, or shock due to allergic reactions to allergens in food. "Such a scenario needs to be tested experimentally in order to better understand the relationship between TLR2 and food allergy." (PMID 25309051, 2014).
gallbladder cancer (4 papers, 2012 to 2024). "There is growing evidence showing the impact of TLR2 and TLR9 genetic polymorphisms on risk of gallbladder cancer, cervical cancer, non-Hodgkin lymphoma and endometrial cancer." (PMID 22309608, 2012). "Multiple polymorphisms in genesassociated with the immune system, inflammation, and oxidative stress that have been linkedto the development of gallbladder cancer like PTGS2, TLR2, TLR4, IL1RN, IL10, IL8, CCR5,LXRB, and OGG1." (PMID 28105075, 2016).
gastroesophageal reflux (4 papers, 2021 to 2022). "In addition, the same study showed that FXR and basal TLR2 expression were linked, and TLR2 and FXR were significantly elevated during reflux esophagitis." (PMID 36142861, 2022). "Furthermore, TLR2 expression was increased in reflux esophagitis, BE, and EAC relative to normal esophageal epithelium." (PMID 34439930, 2021). "We hypothesized that TLR2, TLR4 and FXR activate during gastroesophageal reflux and modulate the mucosal injury." (PMID 33686512, 2021).
gingivitis (4 papers, 2018 to 2024). A disorder involving inflammation of the gums; may affect surrounding and supporting structures of the teeth. "Evaluation of the relationship between the salivary sTLR-2 with the paired SEC associated TLR-2 mRNA in the gingivitis cohort suggest a moderate inverse correlation (r2 = 0.5)." (PMID 30571680, 2018). "In this study, we observed that the SEC from the normal, the gingivitis and the CP cohorts exhibit equivalent levels of TLR-2 mRNA." (PMID 30571680, 2018). "In brief, all three types of biofilm strongly up-regulated TLR2 mRNA expression; TLR7 was significantly activated by commensal and gingivitis biofilms; TLR4 expression was only clearly increased by gingivitis biofilm; TLRs 3, 5, and 6 were not significantly affected by the biofilms." (PMID 31448244, 2019).
Glucose intolerance (4 papers, 2019 to 2025). Glucose intolerance (GI) can be defined as dysglycemia that comprises both prediabetes and diabetes. "The GTT study demonstrated marked glucose intolerance in TLR2−/− mice that developed as early as at 5 months of age." (PMID 36555322, 2022).
hepatitis B (4 papers, 2021 to 2023). "Our findings propose on one side, a positive association between TLR2 polymorphisms and hepatitis B activity, and, on the other, the valuable role of IL-6 a good marker of disease progression in chronic HBV-infected patients." (PMID 35119591, 2023). "There may be a positive association between TLR2 rs3804099 polymorphism and hepatitis B activity." (PMID 35119591, 2023). "TLR2 expression was predominantly identified in syncytiotrophoblast and cytotrophoblast cells in the placentas of mothers with hepatitis B virus infection." (PMID 35875205, 2022). "The expression of TLR2 in the placenta of mothers with hepatitis B virus infection was investigated in this study, as well as its relation to the detection of hepatitis B virus in umbilical cord blood as a marker of intrauterine hepatitis B virus exposure." (PMID 35875205, 2022). "TLR-2 activation may be involved in the progression of numerous diseases including viral hepatitis B." (PMID 35119591, 2023).
ileitis (4 papers, 2010 to 2021). "The TLR2 agonists lipoarabinomannan and lipoteichoic acid reduced indomethacin-induced murine ileitis via modulation of TLR4 pathways on macrophages and effects on leukocyte migration." (PMID 29515999, 2018). "Strong inhibitory effect of pectin DM7 on ileitis are illustrated by the reduction in neutrophil influx and cell death in the crypts that was similar to the reduction in mice treated with TLR2 blocking antibodies (p < 0.01)." (PMID 29545800, 2018). "The TLR2 inhibiting properties of low-DM pectin were further confirmed in doxorubicin-induced ileitis in mice." (PMID 29545800, 2018). "The anti-inflammatory effect of low-DM pectins was first studied in human dendritic cells and mouse macrophages in vitro and was subsequently tested in vivo in TLR2-dependent ileitis in a mouse model." (PMID 29545800, 2018). "To demonstrate principle applicability of the acquired structural insights, we tested the pectin efficacy in preventing TLR2-dependent ileitis in a mice model." (PMID 29545800, 2018). "TLR2 signaling is responsible for inflammation in doxorubicin-induced ileitis." (PMID 29545800, 2018). "In addition, we demonstrate the potential clinical applicability of the obtained insights by testing low-DM pectins in a well-established TLR2-dependent ileitis model in which it blocked ileitis as efficacious as TLR2 antibodies." (PMID 29545800, 2018).
infarction (4 papers, 2009 to 2025). A localised pathological necrosis of tissue resulting from obstruction of the blood supply usually by a thrombus, an embolus, or vascular torsion. "TLR2 and TLR4 agonists trigger platelet activation in patients with AMI through NF-kappa B. Previous studies showed that the activation of TLR2 and TLR4 induced the innate immune response, increasing infarction size and influencing ventricular remodeling." (PMID 35463752, 2022). "In animal studies, stimulation or inhibition of TLR2 and TLR4 resulted in corresponding changes in pro-inflammatory cytokines, brain infarct volume, and functional outcomes." (PMID 31159847, 2019). "The TLR2/TLR4/NF-κB pathway exhibited a pronounced activation in the hyperacute phase of AIS, with a discernible correlation between its expression and the prolongation of infarction time." (PMID 40520774, 2025). "Taking the TLR2/TLR4/NF-κB pathway as the entry point, we found that the mRNA and protein expression of TLR2, TLR4, and NF-κB were progressively upregulated with the prolongation of infarction time, and a significant difference was observed in the 12 h compared with the Sham group (⁣∗∗p < 0.01)." (PMID 40520774, 2025).
intestinal inflammation (4 papers, 2011 to 2021). "TLR2–TLR1 inhibition by pectin was also effective in preventing an intestinal disorder in which intestinal inflammation is exacerbated by TLR2 activation." (PMID 29545800, 2018). "This study demonstrates that TLR2, TLR4, TLR8, and TLR9 expression increases in active UC patients, and that the mRNA levels positively correlate with the severity of intestinal inflammation as well as with inflammatory cytokines." (PMID 22185629, 2011).
Kawasaki disease (4 papers, 2012 to 2024). A rare inflammatory disease characterized by an acute febrile, systemic, self-limiting, medium-vessel vasculitis primarily affecting children. "IVIg can decrease TLR2 on monocytes in Kawasaki Disease patients, which is enhanced in Kawasaki Disease." (PMID 23940791, 2013).
kidney inflammation (4 papers, 2013 to 2025). "By investigating multiple inflammatory mediators (CD93, CD36, STAT3, NF-Kappa B, and TLR2/4), our results highlight the therapeutic potential of hAAT in treating kidney inflammation." (PMID 40723823, 2025). "antigens induce kidney inflammation by activating TLR2 and TLR4 receptors." (PMID 32958053, 2020).
legionellosis (4 papers, 2017 to 2025). Any disease caused by Legionella bacteria. "Given that GM-CSF promotes cytokine production in monocytes stimulated through TLR2 alone, we hypothesized that initial TLR signaling is required for GM-CSF to augment cytokine expression during Legionella infection, as Legionella is known to activate TLR signaling (45, –, 52)." (PMID 40470942, 2025).
leukocytosis (4 papers, 2017 to 2026). "The TLR2 2029 CC genotype was associated with elevated liver enzyme levels (OR 3.025; 95% CI 1.321–6.927; p = 0.009) and leukocytosis (OR 2.574; 95% CI 1.129–5.866; p = 0.024)." (PMID 32753695, 2020). "Furthermore, patients with JAK2 mutations or leukocytosis exhibited higher TLR2 expression." (PMID 39157201, 2024). "TLR2 levels were significantly higher in patients with leukocytosis (>10 × 109/l) than those without leukocytosis, with (333.0 ± 22.97 (n = 53) vs. 269 ± 14.45 (n = 43), (P=0.03), respectively." (PMID 39157201, 2024).
Miscarriage (4 papers, 2018 to 2024). A pregnancy that ends at a stage in which the fetus is incapable of surviving on its own, defined as the spontaneous loss of a fetus before the 22th week of pregnancy. "Mutant SNPs in TLR9, IL-10, TLR2, IL-6, and IL-8 genes were found to have statistically significant effect on the risk of miscarriage with help of multiple logistic regression." (PMID 30116270, 2018). "The additional characterization of the macrophage polarization status using the M1 polarization markers TLR2 and iNOS and the M2 polarization markers CCL1 and CX3CR1 confirmed the loss of M2 polarized marcrophages in recurrent miscarriages." (PMID 29949879, 2018). "TLR2, TLR4, IL-6, IL-8, and PGR SNPs can also affect the risk of miscarriage, but in less extent than TLR9 and IL-10." (PMID 30116270, 2018). "TLR2, TLR4, IL-6, IL-8, and PGR SNPs were identified as secondary factors that can also affect the risk of miscarriage." (PMID 30116270, 2018). "↓ TLR2 expression in the cervical epithelium of subjects with miscarriage." (PMID 39885993, 2024). "Additionally, the impact of herpes simplex viruses 1 and 2 on the expression of TLR2, TLR3, TLR4 and TLR8 in predicting miscarriage onset has been studied." (PMID 39273663, 2024).